ADAD2 (adenosine deaminase domain containing 2)
Description:
Required for male fertility and normal male germ cell differentiation.
Synonyms: TENRL; FLJ00337
Tractability: PROTAC: ubiquitination databases record sites on it.
Gene: Protein-coding gene on chromosome 16 (84,191,125 to 84,197,168, forward strand). Ensembl gene ENSG00000140955.
Subcellular location: Nucleus; Cytoplasm
Gene Ontology:
Molecular function: double-stranded RNA adenosine deaminase activity; double-stranded RNA binding; adenosine deaminase activity; RNA binding
Biological process: adenosine to inosine editing; spermatid development; RNA processing
Cellular component: cytoplasm; nucleolus; nucleus
Genetic constraint (gnomAD): Loss-of-function variants: 61 observed, 49.54 expected, observed/expected ratio (o/e) 1.23, 90% interval 1 to 1.52. The synonymous counts are far from expectation, so gnomAD's model fits this gene poorly and the ratio says little. Missense variants: 1,103 observed, 751.52 expected, observed/expected ratio (o/e) 1.47, 90% interval 1.4 to 1.54. Synonymous variants: 543 observed, 350.68 expected, observed/expected ratio (o/e) 1.55, 90% interval 1.44 to 1.66.
Homologues: Orthologues: chimpanzee ADAD2 (99% identical), macaque ADAD2 (95% identical), dog ADAD2 (73% identical), pig ADAD2 (73% identical), rabbit ADAD2 (69% identical), mouse Adad2 (67% identical), rat Adad2 (67% identical), guinea pig ADAD2 (66% identical), zebrafish adad2 (28% identical), Drosophila melanogaster Adar (22% identical), Drosophila melanogaster Adat1 (13% identical), Caenorhabditis elegans stau-1 (12% identical), and 5 more. Paralogues in human: ADAD1 (28% identical), ADARB1 (25% identical), ADAR (24% identical), ADARB2 (24% identical), ADAT1 (17% identical), ILF3 (12% identical), STRBP (12% identical), ILF2 (10% identical), ZFR2 (10% identical), STAU2 (10% identical), ZFR (10% identical), STAU1 (9% identical), and 2 more.
Diseases named in the same sentence as ADAD2 in open-access papers:
ADAD2 is named in the same sentence as 6 diseases in open-access papers, as found by Europe PMC text mining. Sharing a sentence is not in itself a finding about the gene and the disease. The quoted sentences say what the papers report.
male infertility (3 papers, 2023 to 2025). The inability of the male to effect fertilization of an ovum after a specified period of unprotected intercourse. "Apart from the ADAD2 gene, several pathogenic variants associated with male infertility in other genes have also been reported, many of which appear to be especially prevalent in specific populations." (PMID 37325547, 2023). "Our work provides preliminary clues for genetic counselling of ADAD2 mutation-associated male infertility." (PMID 37325547, 2023). "The identified ADAD2 mutations were further verified by Sanger sequencing and found to be co-segregated with male infertility in the respective families." (PMID 37325547, 2023). "Taken together, our results suggested that ROSI could be a potential treatment for male infertility due to Adad2 mutations." (PMID 37325547, 2023). "Rnf17 mutant males have been shown to exhibit severe post-meiotic germ cell loss culminating in total male infertility and previously published analyses of Adad2 mutant testis histology suggest a similar profile of germ cell loss during round spermatid development." (PMID 37428816, 2023). "Thus, we speculated that these identified mutations in ADAD2 are likely the cause of male infertility in the three families." (PMID 37325547, 2023). "Next-generation sequencing has contributed to the identification of several unknown genetic alterations in the context of male infertility and azoospermia including FANCA, PLK4, WKN3, MEI1, ADAD2, and TEX11." (PMID 40747475, 2025).
Azoospermia (2 papers, 2023 to 2025). Absence of any measurable level of sperm,whereby spermatozoa cannot be observed even after centrifugation of the semen pellet. "Biallelic missense and frameshift mutations in ADAD2 disrupt the differentiation of round spermatids to spermatozoa causing azoospermia in humans and mice." (PMID 37325547, 2023).
infertile (2 papers, 2023 to 2025). "Similar to the ADAD2-mutation-carrying patients, the Adad2Mut/Mut male mice were infertile with significant reductions in testicular size and an absence of spermatozoa in the epididymides." (PMID 37325547, 2023). "Although it is not known whether the remaining genes may lead to female infertility, it is noteworthy that in seven of them (ADAD2, AR, C1orf146, MLH3, RAD21L1, SYCP3, and TERB1), the corresponding female KO mice are infertile." (PMID 40896145, 2025). "In mice, the lack of the RNA-binding protein ADAD2 leads to a complete absence of sperm in epididymides due to failure of spemiogenesis, but the spermatogenic effects of ADAD2 mutations in human NOA-associated infertility require functional verification." (PMID 37325547, 2023).
teratospermia (2 papers, 2020 to 2022). "Mutation of either ADAD1 or ADAD2 resulted in males sterility with ADAD1 mutant mice displaying teratozoospermia." (PMID 35173218, 2022). "Mutation of either Adad resulted in complete male sterility with Adad1 mutants displaying severe teratospermia and Adad2 mutant germ cells unable to progress beyond round spermatid." (PMID 32665638, 2020).
amyloid (1 paper, 2016). "The precuneus and caudate nucleus were chosen for analyses, as they are known to show early amyloid deposition in ADAD2." (PMID 27381087, 2016).
ADAD2 also shares sentences with these, for which no sentence is quoted: female infertility (1 paper).